FGB (fibrinogen beta chain)
Diseases named in the same sentence as FGB in open-access papers (continued):
Sharing a sentence is not in itself a finding about the gene and the disease.
bladder cancer (5 papers, 2018 to 2025). "The expression of FGB increased with stage (p < 0.001) in bladder cancer and is a potential marker to characterize and diagnose bladder cancer." (PMID 30733650, 2019). "Similarly, urinary FGB and tyrosine-phosphorylated proteins have been proposed as biomarkers for bladder cancer diagnosis." (PMID 40433663, 2025). "FGB levels significantly differ in the urinary tracts of patients with bladder cancer compared with those of controls and are elevated in bladder cancer tissue compared with those of morphologically normal tissue, indicating that FGB is a potential biomarker for bladder cancer." (PMID 34737948, 2021). "Importantly, one specific peptide, produced by the cleavage of fibrinogen beta chain (FGB) was frequently identified as cancer biomarker in three previously published CE-MS studies, investigating bladder cancer, renal cell carcinoma and pancreatic cancer respectively." (PMID 29588543, 2018).
breast carcinoma (5 papers, 2022 to 2025). "Although its role in NTM infection remains unclear, studies have shown that FGB is dysregulated in various diseases, such as renal cell carcinoma, malignant pulmonary nodules, and breast cancer, and is associated with disease progression." (PMID 41428679, 2025). "The expression data of ECM fiber-encoding genes (e.g., COL1A1, COL1A2, FGA, FGB, FGG, ELN, FN1, and VTN) from 1358 patients with breast cancer were used for Kaplan–Meier overall survival analysis." (PMID 37369642, 2023). "This present study is aimed at exploring the FGB expression in breast cancer (BC) and the role of FGB in BC." (PMID 36438895, 2022). "Others, such as COL18A1, TGFBI, FGB, ITIH2, ITIH4, and TNC among others, were overrepresented in 3 of 4 signatures and also expressed in mammary carcinoma xenografts." (PMID 37098922, 2023).
bleeding disorder (4 papers, 2014 to 2024). "Pathogenic dominant variants in FGB cause reduced levels of fibrinogen, altered fibrinogen activity, or both, which predisposes to either arterial/venous thromboses or a bleeding disorder." (PMID 35456463, 2022). "Congenital fibrinogen disorders (CFDs) are rare bleeding disorders (RBDs) caused by mutations in 1 of the 3 fibrinogen genes (FGA, FGB, and FGG)." (PMID 38953055, 2024). "Congenital fibrinogen deficiencies are rare bleeding disorders, characterized by extensive genetic heterogeneity in all the three genes: FGA, FGB, and FGG (enconding the Aα, Bβ, and γ chain, respectively)." (PMID 32610551, 2020). "Mutations in three genes (FGA, FGB, FGG) encoding fibrinogen α-, β- and γ-chains lead to congenital fibrinogen deficiency, which is an extremely rare hereditary bleeding disorder, affecting 1 in 1,000,000 individuals." (PMID 25275492, 2014).
hepatocellular carcinoma (4 papers, 2018 to 2025). A malignant tumor that arises from hepatocytes. "All of these provide strong evidence that APOC3, APOH, HPX, and FGB can be used as biomarkers for hepatocellular carcinoma." (PMID 35449866, 2022). "In HCC, FGB functions in portal vein tumor thrombus formation, FGG activating epithelial to mesenchymal transition to promote migration and invasion in hepatocellular carcinoma cells." (PMID 39600945, 2024). "Thus, we verified whether the Fibrinogen β-chain (FGB) transcript was expressed in PBMCs by performing a semi-quantitative RT-PCR, using the human hepatocellular carcinoma HepG2 cell line as a positive control." (PMID 29540212, 2018).
renal cell carcinoma (4 papers, 2018 to 2025). "Similarly, the fibrinogen β chain (FGB) gene has been revealed to be related with renal cell carcinoma invasion and metastasis." (PMID 35449866, 2022). "Another study showed that SIRT1 inhibited renal cell carcinoma (RCC) cell proliferation by inhibiting the expression of the FGB gene, and overexpression of FGB rescued inhibition of SIRT1 overexpression on the proliferation of RCC cells." (PMID 38213743, 2024).
Stroke (4 papers, 2011 to 2022). Sudden impairment of blood flow to a part of the brain due to occlusion or rupture of an artery to the brain. "GenHAT also showed that stroke risk was higher on lisinopril versus amlodipine in common GG homozygotes of fibrinogen beta (FGB) gene, which codes for a polypeptide of the coagulation factor fibrinogen." (PMID 22135769, 2011). "In the present study our hypothesis is that the FGB −455 G/A polymorphism might interact with smoking and interfere sex specific longterm survival after stroke." (PMID 24957141, 2014). "The SAM cohort does not comprise stroke patients under 55 years old and the association of FGB −455 G/A polymorphism with poor survival could not be assessed in premenopausal women." (PMID 24957141, 2014).
thrombosis (4 papers, 2018 to 2025). "A family study was conducted on the proband (II-2), who carries the FGB.C130T:p.R44C variant, previously associated with thrombosis." (PMID 39805289, 2025). "For instance, the p.Arg554Cys mutations in the FGA gene, the p.Ala68Thr mutation in the FGB gene, and the p.Asp364Val mutation in the FGG gene have all been linked to thrombosis." (PMID 41030265, 2025). "Coagulation-related factors, such as F2, SERPIND1, SERPINF2, SERPINA3, FGA, FGB, and FGG, are also downregulated, leading to coagulation dysfunction in the body, which is not conducive to post-exercise recovery and can even lead to thrombosis in severe cases." (PMID 40646880, 2025).
atherosclerosis (3 papers, 2015 to 2024). A disease characterized by the build-up of fatty material and calcium deposition in the arterial wall resulting in partial or complete occlusion of the arterial lumen. "Periodontal microbiome infection is associated with significant decreases in Apoa1, Apob, Birc3, Fga, FgB genes that are associated with atherosclerosis." (PMID 26619277, 2015). "A number of previous studies have shown that plasma FG levels may play an important role in the pathogenesis of atherosclerosis, and certain FGB gene polymorphisms are considered a common risk factor for increased plasma FG levels." (PMID 26710338, 2015). "In the genomic regions shared by GlycA and atherosclerosis, five nonsynonymous exonic SNPs were mapped to genes FGB, SLC22A1, LPL, SERPINA1, and ANGPTL4, with the following high PPs, H3: 94.5%, H4: 96.8%, H4: 73.7%, H4: 97.2%, and H4: 100%." (PMID 38892172, 2024).
endometriosis (3 papers, 2017 to 2025). The growth of functional endometrial tissue in anatomic sites outside the uterine body. "Also, a FGB polymorphism promotes increased risk of endometriosis." (PMID 39836475, 2025). "Notably, the study uncovers two previously unknown genes, KIR2DL3 and FGB, in endometriosis, contributing to the understanding of potential genetic factors in the disease." (PMID 37662927, 2023). "We found that, except for FGB, KIR2DL1, and KIR2DL3, all other hub genes showed significantly different expression levels in the endometriosis and normal control groups." (PMID 37662927, 2023).
gastric cancer (3 papers, 2018 to 2024). A primary or metastatic malignant neoplasm involving the stomach. "Although FGB has been investigated as a potential biomarker for various diseases, including preeclampsia, gastric carcinoma, disseminated intravascular coagulation, and oral squamous cell carcinoma, the relationship between FGB and AVN remains unclear." (PMID 38825675, 2024).
metabolic syndrome (3 papers, 2020 to 2025). A cluster of metabolic risk factors for CARDIOVASCULAR DISEASES and TYPE 2 DIABETES MELLITUS. "The TyG-i, a composite measure derived from TG and FGB levels, has been posited as a viable biomarker for metabolic syndromes, atherogenesis, and cardiovascular pathology." (PMID 38500198, 2024). "It is a potential link between TNBC development and metabolic syndrome; it inhibits EMT by targeting FGB." (PMID 41441396, 2025).
coagulation disorders (2 papers, 2019 to 2021). "FGB is cleaved by thrombin to yield monomers that polymerize into insoluble fibrin, usually associated with coagulation disorders." (PMID 33535467, 2021).
insomnia (2 papers, 2021 to 2022). A sleep disorder characterized by difficulty in falling asleep and/or remaining asleep. "In the results, HP, FGA, FGG, FGB, and MMP9 were upregulated in patients with insomnia, and FN1, APP, EGF, AHSG, and IGF1 were downregulated compared with controls." (PMID 35958162, 2022). "Among them, HP, MMP9, FGA, FGB, and FGG were validated as upregulated, and APP, AHSG, and IGF1 were downregulated in patients with insomnia." (PMID 35958162, 2022). "Among them, the expression of F2, HP, FGA, FGB, FGG, and ApoB were upregulated in insomnia patients with wakefulness, and A2M, AHSG, APP, and ApoA1 were downregulated." (PMID 33511209, 2021). "On the other hand, through Western blot experiments, we verified that the expression of FGG, FGB, FGA, APOB, F2, and HP was upregulated in insomnia patients with wakefulness compared with the control, while the expression of A2M, AHSG, and APOA1 was downregulated." (PMID 33511209, 2021).
laryngeal carcinoma (2 papers, 2015 to 2019). Carcinoma that arises from the laryngeal epithelium. "Otherwise, using iTRAQ and mass spectrometry analysis, researchers found that FGB was significantly up-regulated in laryngeal carcinoma tissues." (PMID 30733650, 2019). "It noted up-regulation of S100A2, FGB, KRT17, FN1 and POSTN in laryngeal carcinoma tissues, as compared with normal tissue." (PMID 25874882, 2015).
lung adenocarcinoma (2 papers, 2019 to 2021). A carcinoma that arises from the lung and is characterized by the presence of malignant glandular epithelial cells. "Elevated FGB expression was reported in lung adenocarcinoma, suggesting a potential role as a biomarker." (PMID 33804769, 2021).
myopia (2 papers, 2019 to 2023). "Antithrombin-III (SERPINC1), fibrinogen gamma chain (FGG), and fibrinogen beta chain (FGB) are potential novel biomarkers for myopia." (PMID 36674802, 2023).
Obesity (2 papers, 2020 to 2025). Accumulation of substantial excess body fat. "Our results provide evidence for the main effects of the FGB genes on IMT, for the interaction of CRP SNP rs1130864 and rs3093059 with gender on IMT, and with obesity on IMT, hs-CRP and fibrinogen levels." (PMID 32214403, 2020). "Studying obesity with and without OSA, changes (unadjusted for multiple comparisons) in some peptides belonging to CDH13, FGB, COL1A1, and COL3A1 were also identified." (PMID 39858454, 2025).
pancreatic cancer (2 papers, 2018 to 2021). "Knockdown of NR5A2 in pancreatic cancer decreased the expression of FGB, TWIST, SNAIL, MMP9, MMP3, MMP2, and Vimentin, as well as increased the expression of the epithelial markers β-catenin and E-cadherin." (PMID 34277436, 2021).
rectal cancer (2 papers, 2021 to 2022). A primary or metastatic malignant neoplasm that affects the rectum. "It is noteworthy that increased levels of FGB observed in pre-treatment tissue biopsies were prognostic for poor response in rectal cancer patients subsequently treated with neoadjuvant chemo-radiotherapy." (PMID 35205741, 2022). "FGB, which is cleaved to fibrin during the formation of blood clots, is present at higher levels in poor responders with rectal cancer, and a clinical validation study confirmed the predictive value of FGB." (PMID 34737948, 2021).
viral infection (2 papers, 2022 to 2025). "In particular, vWF, HRG, PROS1, GC, F2, FGA, and FGB proteins, which are responsible for the expansion of vessels and new vessel formation, modulate blood coagulation and mitigate against vasoconstriction and coagulation caused by virus infection." (PMID 35401544, 2022).
aneurysm (1 paper, 2022). Bulging or ballooning in an area of an artery secondary to arterial wall weakening. "miR-139-5p can target FGB and inhibit FGB expression, thereby improving the progression of aneurysm." (PMID 35469231, 2022). "Here, we speculated that miR-139-5p could target and inhibit FGB expression and improve aneurysm progression." (PMID 35469231, 2022). "Our previous studies found that FGB was significantly upregulated in the intracranial aneurysm group and ruptured aneurysm group by mass spectrometry analysis (data not shown)." (PMID 35469231, 2022).
Arterial thrombosis (1 paper, 2017). The formation of a blood clot inside an artery. "A novel mutation was identified in exon 2 of FGB caused by c.221G> T† substitution, predicting the replacement of Arginine at position 74 with a Leucine (p.Arg74Leu†) in a proband from a Kurdish family with dysfibrinogenaemia and familial venous and arterial thrombosis." (PMID 27812779, 2017).
atrial fibrillation (1 paper, 2023). A disorder characterized by an electrocardiographic finding of a supraventricular arrhythmia characterized by the replacement of consistent P waves by rapid oscillations or fibrillatory waves that vary in size, shape and timing and are accompanied by an irregular ventricular response. "Only one study has tried to associate FGB with LAA thrombus formation in patients with atrial fibrillation, but the sample size was too small, and the result was negative as well." (PMID 37834890, 2023).
biliary atresia (1 paper, 2025). A rare, biliary tract disease characterized by progressive obliterative cholangiopathy of the intra- and extrahepatic bile ducts, occurring in the embryonic/ perinatal period, leading to severe and persistent neonatal jaundice and acholic stool. "A previous systematic review of FGB non‐visualisation calculated different rates of isolated FGB agenesis, biliary atresia, cystic fibrosis and chromosomal abnormalities." (PMID 39702857, 2025).
brain infarction (1 paper, 2022). Tissue necrosis in any area of the brain, including the cerebral hemispheres, the cerebellum, and the brain stem. "A novel missense variant of uncertain significance in FGB, which encodes fibrinogen β chain, was identified in one of the two tested patients suffering from brain infarction." (PMID 35456463, 2022).
brucellosis (1 paper, 2024). Brucellosis is a bacterial infection that spreads from animals to people via unpasteurized dairy products or by exposure to contaminated animal products or infected animals. "The findings demonstrated that while these proteins were elevated during the acute phase of Brucellosis, CRP, FGB, LYZ, and AAT did not return to the baseline levels observed in healthy controls in chronic patients." (PMID 39872944, 2024).
cardiac hypertrophy (1 paper, 2020). "The sets include functions such as PI3K and MAPK kinase signaling pathways, involved in HF-related cardiac hypertrophy, or fibrinolysis and coagulation processes (e.g. FGB, SERPINE1 or SERPING1) and growth factors (e.g. FGF1 or PDGF) related to MD induction." (PMID 32053711, 2020).
cardioembolic stroke (1 paper, 2020). "FGB mutation can elevate the level of plasma fibrinogen in AF patients, and thereby played a role in cardioembolic stroke." (PMID 33041871, 2020).
Coats disease (1 paper, 2016). Coats disease (CD) is an idiopathic disorder characterized by retinal telangiectasia with deposition of intraretinal or subretinal exudates, potentially leading to retinal detachment and unilateral blindness. "Interestingly, several genes, including APOC1 and FGB, were up-regulated in the AH samples of the patients with Coats' disease." (PMID 27416065, 2016).
endometrial cancer (1 paper, 2017). Primary or metastatic malignant neoplasm involving the endometrium (mucous membrane that lines the endometrial cavity). "Western blotting verification data demonstrated that costars family protein ABRACL, phosphoglycerate mutase 2 were present only in endometrial cancer uterine aspirate while fibrinogen beta chain, annexin A3 were also present in healthy aspirates." (PMID 29312627, 2017). "In this study, western blot (WB) analysis from ten endometrial cancer vs six normal endometrium was used to validate the abundance of the four proteins which discriminate unambiguously between cases and controls (ABRACL, PGAM2, FGB, ANXA3)." (PMID 29312627, 2017). "From the discovery phase, four proteins (costars family protein ABRACL, phosphoglycerate mutase 2, fibrinogen beta chain, annexin A3) were found to be present in the uterine aspirate of endometrial cancers and not in healthy aspirates." (PMID 29312627, 2017).
endometritis (1 paper, 2023). An acute or chronic, usually bacterial infectious process affecting the endometrium. "In our study, the level of FGG transcripts decreased in the liver of the castrated bucks that were administered a mixture of dried extracts from R. officinalis and C. longa, while high levels of FGB and FGG were found in cattle liver, wherein their expression increased during endometritis." (PMID 37895281, 2023).
endothelial dysfunction (1 paper, 2018). In vascular diseases, endothelial dysfunction is a systemic pathological state of the endothelium (the inner lining of blood vessels) and can be broadly defined as an imbalance between vasodilating and vasoconstricting substances produced by (or acting on) the endothelium. "In our study, among differentially expressed proteins were PLG, SERPING1, SERPINC1, APOA2, FGB, A2M, which are related to endothelial dysfunction, coagulation processes and pro-atherogenic alteration mechanisms." (PMID 29755368, 2018).
fibrosis (1 paper, 2023). the formation of excess fibrous connective tissue in an organ or tissue in a reparative or reactive process. "Top novel candidate genes with high entropy values include VTN, FGB and FGG, which are associated with changes observed in fibrosis under chronic liver damage condition." (PMID 36944690, 2023).
heart failure (1 paper, 2025). Inability of the heart to pump blood at an adequate rate to meet tissue metabolic requirements. "FGB gene upregulation was also observed, which has been associated with heart failure and attack." (PMID 40596362, 2025).
hemophilia A (1 paper, 2021). The most common form of hemophilia characterized by spontaneous or prolonged hemorrhages due to factor VIII deficiency. "In severe cases, although hemophilia A was combined with other bleeding factor deficiencies, the genetic alterations in the second gene (FGB or FGG (P29, P30, P31), F9 (P28)) did not change the severity of the bleeding episodes." (PMID 33477601, 2021).
hyperglycaemia (1 paper, 2025). "Prediabetes and T2D are marked by chronic hyperglycaemia, characterised by elevated levels of FGB, HbA1c, insulin and HOMA-IR, along with impaired β-cell function." (PMID 41280283, 2025).
hypodysfibrinogenemia (1 paper, 2024). "Interestingly, the mutation c.510T>A (p.Asn170Lys) in FGB exon 4 was first identified in Chinese patients with congenital hypodysfibrinogenemia, which has been shown to affect the quality and quantity of the fibrinogen." (PMID 38953055, 2024). "Our study reported 3 patients with hypodysfibrinogenemia from the same family who had 3 compound missense mutations in the FGA, FGB, and FGG genes." (PMID 38953055, 2024).
intracranial aneurysm (1 paper, 2022). "In the present study, the expression of FGB in the intracranial aneurysm was remarkedly upregulated." (PMID 35469231, 2022). "miR-139-5p was suppressed and FGB was upregulated in intracranial aneurysm samples." (PMID 35469231, 2022). "However, we found that FGB in intracranial aneurysm samples was overexpressed compared to normal samples." (PMID 35469231, 2022). "Moreover, we observed the levels of IL-1β and tumor necrosis factor a (TNF-α) increase with the upregulation of FGB in human intracranial aneurysm cells." (PMID 35469231, 2022).
ischemia (1 paper, 2023). A hypoperfusion of the BLOOD through an organ or tissue caused by a PATHOLOGIC CONSTRICTION or obstruction of its BLOOD VESSELS, or an absence of BLOOD CIRCULATION. "FGB and FGG are fibrinogen chains that could increase with increased retinal vascular permeability due to ischemia or inflammation." (PMID 36674802, 2023).